BAP1 (BRCA1 associated deubiquitinase 1)
Diseases named in the same sentence as BAP1 in open-access papers (continued):
Sharing a sentence is not in itself a finding about the gene and the disease.
tumor (continued). "According to Cancer Genome Interpreter (CGI) analysis, alterations in SETD2, BAP1, FLT4 and PTEN genes were reported as known drivers in several tumor types, and events in FGFR4 and NSD1 genes were classified as predicted drivers." (PMID 33668731, 2021). "Using tissue microarrays of tumor samples from MPM patients, we found a strong inverse correlation between BAP1 and TRAIL receptor expression." (PMID 34597666, 2021). "Some DUBs, including UCHL1, BAP1 and CYLD, are described as displaying intrinsic oncogenic or tumor suppressor activities." (PMID 34315490, 2021). "BAP1 and ASXL proteins form mutually exclusive complexes of the PR-DUB tumour suppressor, which maintains transcriptional silencing of polycomb target genes." (PMID 34170818, 2021). "In summary, our findings demonstrate that BAP1 is an important deubiquitinase of PTEN for its stability and the BAP1‐PTEN signaling axis plays a crucial role in tumor suppression." (PMID 33155366, 2021). "Depletion of BAP1 leads to a dramatic decrease of MLL3 COMPASS and its subunit, H3K27 demethylase UTX, leading to further repression of multiple tumor suppressors, such as GRHL2, RBMS3, DACT2, and DSC330." (PMID 33483476, 2021). "BAP1 catalytic inhibitors have been shown to inhibit truncated-ASXL1-driven leukemic gene expression and halt tumor progression in vivo." (PMID 34868917, 2021). "Frozen tumor tissues and plasma were used to measure PBRM1, BAP1, SET domain-containing 2 (SETD2), KDM5C, FOXC2, CLIP4, AQP1, DDX11, BAIAP2L1, and TMEM38B mRNA levels, and correlation with the Fuhrman grade was investigated." (PMID 32392781, 2020). "In this regard, the authors further found that BAP-1 (a chromatin modulator and potential tumor suppressor,) directly regulates NEAT1 expression and that BTC cells and patient samples show inverse BAP-1/NEAT1 expression patterns." (PMID 32331331, 2020). "As expected, tumor cells cluster most strongly according to the GEP-based clinical prognostic classifier, with the primary division occurring between class 1 (BAP1 wild-type) and class 2 (BAP1 mutant) tumors." (PMID 31980621, 2020). "In one of these subclasses, we found frequent BAP1 (n = 22) and PBRM1 (n = 16) alterations—including 5 cases with BAP1 and PBRM1 aberrations in the same tumor (total n = 33 tumors)." (PMID 33087175, 2020). "Although these data may apparently contradict the negative prognostic value of BAP1 loss/mutation, however, they further support the important role of additional factors in the pathophysiological mechanisms underlying tumor growth, immune escape and prognosis in UM." (PMID 30653520, 2019). "The inactivation of BAP1 and PBRM1 mainly contribute to different pathways of tumor evolution, being almost mutually exclusive events conferring different prognosis." (PMID 31861590, 2019). "The BAP1 protein contains binding domains for BRCA1 and BARD1, enzymes that form a heterodimeric complex that functions as a tumor suppressor." (PMID 31382494, 2019). "Within the group of monosomy 3 tumours (n = 21), this association could not be established, but that may be due to a small sample size as only four out of 21 tumours with monosomy 3 had not lost their BAP1 expression." (PMID 31337000, 2019). "Although earlier studies suggested that BAP1 function is through modulation of the BRCA1, later studies showed that it is an independent tumor suppressor gene." (PMID 30716094, 2019). "To explore the potential role of BAP1 in ICC, we first evaluated messenger RNA (mRNA) expression of BAP1 in 60 paired ICC samples and matched adjacent non-tumor liver tissues." (PMID 30305612, 2018).
tumor (continued). "In summary, our study demonstrated that BAP1, which is frequently downregulated in ICC, was a putative tumor suppressor in human ICC." (PMID 30305612, 2018). "The results showed that BAP1 mRNA expression was downregulated in 73.3% (44/60) of ICC tissues, relative to the adjacent non-tumor liver tissues (P = 0.039)." (PMID 30305612, 2018). "Taken together, our data suggested that BAP1 negatively regulated the ERK1/2 and JNK/c-Jun signaling pathways to exert its tumor-suppressive functions in ICC." (PMID 30305612, 2018). "6p+ Was usually present in 100% of tumor cells in SF3B1-mutant tumors but only in a subclone in EIF1AX-mutant and BAP1-mutant tumors; 8q+ was usually present in 100% of tumor cells in SF3B1-mutant and BAP1-mutant tumors but was rarely present in EIF1AX tumors." (PMID 29317634, 2018). "Moreover, reduced BAP1 levels in “normal” cells, induce a Warburg effect, i.e., a shift from oxidative phosphorylation (Kreb’s cycle) to aerobic glycolysis, a process that might prime these “normal” cells for malignant transformation and tumor growth." (PMID 30455474, 2018). "In the present study, we identify alterations in long non-coding RNA gene expression as a contributor to tumor cell phenotype and differential therapeutic sensitivity of CCA cells that is related to BAP1 expression." (PMID 28122578, 2017). "The remaining cases with germline mutations, which were predominantly missense mutations, were associated with less typical pedigrees and tumours lacking a characteristic BAP1-associated histopathological appearances, but may still represent less penetrant variants." (PMID 28062663, 2017). "In tumor BC_2R, focal SCNAs were present in regions covering VHL, SEDT2, PBRM1 and BAP1, while focal SCNAs were only detected in the region covering VHL in the left tumor (BC_2L)." (PMID 27383411, 2016). "Finally, we tested whether BAP1 promoted HCC1806 tumour growth through KLF5." (PMID 26419610, 2015). "Two recent whole exome-sequencing studies of ICC revealed a key role for chromatin remodeling genes BAP1, ARID1A and PBRM1 in the development of these tumours." (PMID 24867389, 2014). "Hence, the precise and dynamic balance between BAP1 and PRC1 is imperative for maintaining MHC-II gene expression and orchestrating the switch between the “hot” or “cold” status of tumor cells." (PMID 39817454, 2025). "Therefore, to study how BAP1 impacts TME and tumor growth, we inoculated BAP1-WT and -KO A20 cells, which were originally derived from BALB/c mice, into normal BALB/c mice." (PMID 39817454, 2025). "Similarly, the identification of atypical lesions, like BAP1-inactivated melanocytic tumors, requires nuanced clinical judgment and coordination with molecular diagnostics to guide patient management, even when the associated tumor type is not the presenting malignancy." (PMID 40649916, 2025). "Functional studies reveal that BAP1 reduces H2Aub levels at the SLC7A11 promoter through its enzymatic activity, thereby inhibiting cystine uptake and inducing ferroptosis—a process demonstrating significant tumor suppression in animal models." (PMID 40919133, 2025). "In conventional ccRCC, the loss of chromosome 3p is a common early event, frequently leading to the simultaneous inactivation of key tumor suppressor genes, including PBRM1, BAP1, and SETD2, all of which are involved in chromatin remodeling and histone regulation." (PMID 40940841, 2025). "Intriguing, high expression of BAP1 protein was only detected in the cytoplasm but not the nucleus of tumor cells in human HCC tumors." (PMID 39984455, 2025). "There was significant increase in tumor size upon BAP1 knockdown in shBAP#3 but not with shBAP1#1, as compared with the shNTC group." (PMID 39984455, 2025). "Strikingly, in our material, a strong negative correlation between BAP1 expression and HLA class I+ tumor cells was present." (PMID 39918475, 2025). "BAP1, characterized by its UCH domain, is a crucial tumor suppressor across various malignancies." (PMID 39048965, 2024).
tumor (continued). "The difference in median volume among the BAP1+/− patients failed to achieve statistical significance (p=0.15), which mitigated the impact of tumor size as a confounding factor for the classification task." (PMID 39669009, 2024). "Notably, within MPM tumors, we detected a significantly increased interaction between tumor cells and CD8+ T cells in tumors with low BAP1 expression compared with those with high BAP1 expression." (PMID 38994676, 2024). "BAP1 protein expression was known for 12 patients of which 8 had a BAP1 negative tumor and 4 had a BAP1 positive tumor (mean ctDNA levels = 4.2 and 3.2, respectively)." (PMID 38319670, 2024). "However, similar to other animal models, monosomy 3 and BAP1 deficiency could not yet be confirmed as a major risk factor for increased tumor growth and metastasis in our CAM model, suggesting the involvement of additional factors or conditions in patients that are not present in in vivo models." (PMID 39056751, 2024). "A BAP1 deletion was found in the MPM671 cell line and tumor." (PMID 37345150, 2023). "Only 0.80% (n = 1) tumor was found to have PALB2, while 18.60% (n = 22) were found to have BAP1." (PMID 36831055, 2023). "We compared the tumor-cell expression profiles of BAP1-mutant tumors versus non-BAP1 and non-PBRM1-mutant tumors using snRNA-seq data and identified 563 differentially expressed genes." (PMID 36973268, 2023). "Notably, consistent with in vitro cellular results and subcutaneous xenograft results, depletion of BAP1 significantly inhibits the growth of implanted tumor cells, but overexpression of MYCN partially rescued BAP1 depletion-mediated cells growth retardation." (PMID 37543638, 2023). "In contrast, tumor burden was not decreased by RSL3 treatment in zebrafishes engrafted with spUM-LB004 which was scored in the clinic BAP1+." (PMID 37321991, 2023). "A significant negative correlation was shown between nuclear BAP1 expression and tumor size and between nuclear BAP1 expression and grade." (PMID 37445575, 2023). "It is worth noting that BAP1 and EZH2 are the only markers that are localized in the nuclei of tumor cells, whereases the IHC analysis of the other markers results in a cytoplasmic staining wherein variable intensity can challenge the detection of a positive signal from the background." (PMID 36900330, 2023). "BAP1 loss/inactivation therefore results in a lack of both of these activities, accelerating tumorigenesis, which indicates that this DUB is a powerful tumor suppressor." (PMID 37009801, 2023). "In line with this notion, we found BAP1 knockdown could inhibit MYCN-amplified NB cells proliferation, migration and tumor growth in BE2C and SH-EP Tet21/N cells and in xenograft mice models which support the notion that BAP1 might be an oncogene in NB." (PMID 37543638, 2023). "In the replication cohort, metabolite abundancies are slightly different in the BAP1 group, with F1-scores of 0.82, 0.59, and 0.59 for patients harboring a BAP1, SF3B1, and EIF1AX-mutated tumor in the negative ion mode, respectively." (PMID 36982149, 2023). "BAP1 was initially shown to localize to the nucleus where its primary interaction was binding to BRCA1 and enhancing its tumor suppressive activity 5, and subsequent researches have revealed that BAP1 acts independently as a tumor suppressor." (PMID 34976173, 2022). "In patient-derived MPM cultures and syngenic murine models, MLN4924 and cisplatin showed anti-tumor effects, regardless of MPM histotype and BAP1 mutational status, increasing DNA damage, inducing S- and G2/M-cell cycle arrest, and apoptosis." (PMID 35197103, 2022). "Of note, BAP1 deletion failed to further decrease tumor cell dissemination in Mel202 SF3B1 mut‐KO clone, suggesting the inhibitory effect of the co‐occurrence of BAP1 deletion and SF3B1 mutation on invasion." (PMID 34706158, 2022). "In the nucleus, BAP1 binds to BRCA1 and enhances its tumor suppressive activity." (PMID 35425712, 2022).
tumor (continued). "In both cases, cytokeratin positive tumours cells corresponded with regions that stained either positive or negative for nuclear BAP1 according to their BAP1 status and were intermingled with cells not stained for cytokeratin." (PMID 36497318, 2022). "Alterations in IDH1, FGF19, RB1, and BAP1 appeared in patients with tumor size reduction, but not in those with non-responding tumors." (PMID 35311147, 2022). "An in vitro study demonstrated that a BAP1 mutant cell line responded to a combination of PARP inhibition and cisplatin supporting BAP1 as target for therapy, with patient trials underway in MPM and other BAP1 altered tumours." (PMID 35637530, 2022). "Since PD-L1 expression on tumor cells has been used widely as a predictive marker for efficacy of ICI therapy, to further analyze the relationship, the expression of BAP1 and PD-L1 in HCC tissues were assessed by immunohistochemistry staining of human HCC tissue microarray." (PMID 34976173, 2022). "BAP1-ASXL2, but not ASXL1-BAP1 complexes, appears to mediate this tumor-suppressive function; overexpression of BAP1 or ASXL2, but not ASXL1, induces senescence, and deletion of the ASXM domain of ASXL2 impairs senescence (human fibroblasts IMR90 cell line)." (PMID 36068610, 2022). "Collectively, these observations suggest that BAP1 deletion preferentially suppresses tumor cell invasion of SF3B1‐mutant Mel202 cells, but not the SF3B1 wild‐type OMM2.3 cells, in xenograft zebrafish models." (PMID 34706158, 2022). "Similar to data observed in the Gq mutant UM cells, ectopic expression of mutant SF3B1, but not the wild‐type SF3B1, combined with BAP1 deletion strongly impaired tumor growth in a nude mouse xenograft model." (PMID 34706158, 2022). "Fittingly, none of our tumor samples carried somatic alterations in other cancer driver genes besides BAP1." (PMID 35885614, 2022). "Several studies have proved the crucial role of BAP1 and PBRM1 in tumor development." (PMID 35918352, 2022). "There was no obvious change in tumor cells disseminated away from yolk sac in vector and BAP1 KO groups of OMM2.3 cells." (PMID 34706158, 2022). "RCC frequent somatic 3p losses, related to three major RCC tumor suppressor genes, namely VHL (located at 3p25.3), BAP1, and PBRM1 (3p21.1), could have masked germline MITF p.E318K alleles (3p13)." (PMID 34067022, 2021). "Compared with ccRCC patients without VTT and the corresponding data in the KIRC, we found a trend of an increased prevalence of BAP1 alterations in both VTT and their matched primary tumor tissues, and alterations of BAP1 have been widely regarded as an unfavorable prognosis biomarker in ccRCC." (PMID 34249685, 2021). "Presence or absence of immunohistochemical BAP1 nuclear staining in tumor cells is currently used for differential diagnosis of MPM." (PMID 32944962, 2021). "This suggests that altered Ca2+ homeostasis may also directly contribute to the tumorigenesis of SMARCA4/2 loss through suppression of apoptosis, as previously shown for other major tumor suppressors PTEN, BAP1, and PML66–68." (PMID 34518526, 2021). "The presence of a higher large basal diameter tumor (p < 0.001), tumor infiltrating lymphocytes (p = 0.020), and a lack of nuclear BAP1 immunostaining (p = 0.001) ocurred significantly more often in the metastatic group." (PMID 34771510, 2021). "Patients in low BAP-1 groups had significantly shorter Kaplan–Meier metastasis-free survival, regardless of tumor region (Log-Rank p ≤ 0.001)." (PMID 33800007, 2021). "Clinical and research use involves binary evaluation of presence or absence of BAP1 nuclear staining, defined as positive when the nuclei of tumor cells exhibit immunoreactivity." (PMID 32944962, 2021).
tumor (continued). "Concluding, expression of YAP/TAZ-related genes correlated with tumor genetics in UM, with a higher activity in M3/BAP1-negative lesions." (PMID 33798262, 2021). "It is not clear if the location of the BAP1 protein in the cell interferes with the tumor suppressor function." (PMID 34771510, 2021). "The lack of nuclear expression and the mislocalization of the BAP1 protein can result in tumor development and/or progression to metastatic disease." (PMID 34771510, 2021). "In one of 40 tumors (3%), 100% of the cells were BAP-1 positive with no tumor having 90–99% BAP-1 positive cells." (PMID 33800007, 2021). "This study effectively determined that BAP1, CDKN2A and NF2 alterations occur in pleural effusion-derived tumour cells at a higher frequency than what is typically seen in MM tumour samples, as well as identifying high frequency alterations for the TRAF7 and LATS2 genes." (PMID 34900693, 2021). "In addition, our previous genome-wide studies have shown that enhancers binding to the BAP1 complex are responsible for the recruitment of MLL3 COMPASS, which functions as a general tumor suppressor." (PMID 33483476, 2021). "As a particular SMG of C1, BAP1 has been certified to block cystine uptake by inhibiting the expression of SLC7A11, leading to lipid peroxidation and ferroptosis, thereby inhibiting tumor progression." (PMID 33738257, 2021). "Furthermore, to investigate the functional correlation between BAP1 and PTEN in vivo, xenografted tumor growth analysis was performed." (PMID 33155366, 2021). "Overall, these results suggest that, although aberrations of BAP1, CDKN2A, and other tumor suppressor genes are the commonest genomic cancer-driving hits in MM, some rare cases of MM might also be driven by genomic dysregulation of MET signaling." (PMID 34884673, 2021). "Regardless of region, analysis of BAP-1 expression adds significant prognostic information beyond tumor size and gene expression class." (PMID 33800007, 2021). "We observed that expression of several YAP/TAZ-related genes correlated with tumor genetics in UM, with a higher activity in M3/BAP1-negative lesions, although the prognostic value of the YAP/TAZ pathway was limited." (PMID 33798262, 2021). "A prospective study examining frozen tissue qRT-PCR of AQP1, DDX11, BAIAP2L1, and six previously identified genes (PBRM1, BAP1, SETD2, KDM5C, FOXC2, and CLIP4) showed that expression of DDX11 was a significant factor for predicting tumor aggressiveness based on Fuhrman grade." (PMID 31963294, 2020). "Originally identified as an interacting partner of the BRCA1 tumor suppressor, BAP1 augments tumor suppressor functions but has not been identified as a DUB for BRCA1." (PMID 32549302, 2020). "BAP1 promotes DSB repair, likely as a part of its tumor suppressor function." (PMID 33230107, 2020). "Individually, BAP1-classification was a significant predictor (hazard coefficient 26.0, 95% CI 3.3–205.9, p = 0.002), but not tumor diameter (hazard coefficient 1.2, 95% CI 0.9–1.6, p = 0.12)." (PMID 31623293, 2019). "This matter falls outside the scope of this article, as tumor tissue analysis was not performed before germline BAP1 analysis." (PMID 31382694, 2019). "The primary tumour and the matched liver metastasis of case SPN13 sharing a deleterious mutation of BAP1 featured heterogeneous and homogenously negative staining for the gene product, respectively." (PMID 30306561, 2019). "When we analysed the relationship of 8q gain within tumours that still expressed BAP1 (n = 20), 8q gain was not related to MVD (p = 0.59)." (PMID 31337000, 2019).